SFRP1 (secreted frizzled related protein 1)
Description:
Soluble frizzled-related proteins (sFRPS) function as modulators of Wnt signaling through direct interaction with Wnts. They have a role in regulating cell growth and differentiation in specific cell types. SFRP1 decreases intracellular beta-catenin levels (By similarity). Has antiproliferative effects on vascular cells, in vitro and in vivo, and can induce, in vivo, an angiogenic response. In vascular cell cycle, delays the G1 phase and entry into the S phase (By similarity). In kidney development, inhibits tubule formation and bud growth in metanephroi (By similarity). Inhibits WNT1/WNT4-mediated TCF-dependent transcription.
Synonyms: FRP-1; FRP; FRP1; SARP2; FrzA
Tractability: Small molecule: a high-quality ligand is known; it belongs to a druggable protein family. Antibody: its Gene Ontology location is reachable by antibodies, with high confidence; UniProt places it where antibodies can reach, with medium confidence; UniProt predicts a signal peptide or a membrane-spanning region. PROTAC: its protein half-life has been measured; a small molecule that binds it is known.
Target class: Secreted protein
Gene: Protein-coding gene on chromosome 8 (41,261,956 to 41,309,511, reverse strand). Ensembl gene ENSG00000104332.
Subcellular location: Secreted
Pathways (Reactome):
Signal Transduction: Negative regulation of TCF-dependent signaling by WNT ligand antagonists; TCF dependent signaling in response to WNT
Gene Ontology:
Molecular function: cysteine-type endopeptidase activity; frizzled binding; heparin binding; identical protein binding; protein binding; Wnt-protein binding
Biological process: canonical Wnt signaling pathway; cellular response to BMP stimulus; cellular response to estradiol stimulus; cellular response to estrogen stimulus; cellular response to hypoxia; cellular response to interleukin-1; cellular response to prostaglandin E stimulus; cellular response to starvation; cellular response to transforming growth factor beta stimulus; cellular response to tumor necrosis factor; cellular response to vitamin D; dorsal/ventral axis specification; hematopoietic progenitor cell differentiation; hematopoietic stem cell differentiation; negative regulation of androgen receptor signaling pathway; negative regulation of apoptotic process; negative regulation of B cell differentiation; negative regulation of bone remodeling; negative regulation of canonical Wnt signaling pathway; negative regulation of cell growth; negative regulation of cell migration; negative regulation of cell population proliferation; negative regulation of DNA-templated transcription; negative regulation of epithelial cell proliferation; negative regulation of epithelial to mesenchymal transition; and 36 more
Cellular component: cell surface; cytosol; extracellular exosome; extracellular matrix; extracellular region; plasma membrane
Genetic constraint (gnomAD): Loss-of-function variants: 9 observed, 23.36 expected, observed/expected ratio (o/e) 0.39, 90% interval 0.23 to 0.67. The upper end of that interval is the gene's LOEUF score, 0.67, which puts it in group 2 of 6, group 1 being the genes least tolerant of losing a copy. Missense variants: 340 observed, 403.13 expected, observed/expected ratio (o/e) 0.84, 90% interval 0.77 to 0.92. Synonymous variants: 176 observed, 170.84 expected, observed/expected ratio (o/e) 1.03, 90% interval 0.91 to 1.17.
Homologues: Orthologues: chimpanzee SFRP1 (99% identical), macaque SFRP1 (99% identical), dog SFRP1 (96% identical), rat Sfrp1 (95% identical), mouse Sfrp1 (95% identical), pig SFRP1 (94% identical), guinea pig SFRP1 (92% identical), tropical clawed frog sfrp1 (63% identical), zebrafish sfrp1a (58% identical), zebrafish sfrp1b (55% identical), Caenorhabditis elegans sfrp-1 (33% identical), Drosophila melanogaster fz3 (24% identical). Paralogues in human: SFRP5 (55% identical), SFRP2 (38% identical), FZD7 (28% identical), FZD1 (26% identical), FZD2 (26% identical), FZD4 (25% identical), FZD10 (24% identical), FZD8 (24% identical), FZD6 (24% identical), FZD9 (24% identical), FZD5 (23% identical), SMO (22% identical), and 3 more.
Diseases named in the same sentence as SFRP1 in open-access papers:
SFRP1 is named in the same sentence as 221 diseases in open-access papers, as found by Europe PMC text mining. Sharing a sentence is not in itself a finding about the gene and the disease. The quoted sentences say what the papers report.
breast carcinoma (107 papers, 2006 to 2025). "The loss of SFRP1 has been linked with the progression of breast cancer and a poorer prognosis in early-stage tumors." (PMID 38444019, 2024). "A human transcriptome array on ERα-positive breast cancer continuum of risk identified Secreted Frizzled-Related Protein 1 (SFRP1) as decreased during breast cancer progression." (PMID 37190179, 2023). "Considering that SFRP1 is associated with both breast cancer outcome and parity status, future survival analyses aiming to investigate the potential of SFRP1 to be used as a prognostic factor should be adjusted for parity status." (PMID 37190179, 2023). "To corroborate these results, we obtained in vitro in breast cancer cell lines and performed public dataset analyses in order to investigate the association between SFRP1 expression and breast cancer patient outcomes." (PMID 37190179, 2023). "Secreted Frizzled-Related Protein 1 (SFRP1) expression is decreased during breast cancer progression and inversely associated with breast tissue age-related lobular involution in women." (PMID 37190179, 2023). "Our study has therefore established for the first time that reduced expression of SFRP1 is significantly associated with metastasis formation in canine mammary cancer." (PMID 37402051, 2023). "Because of the crucial role of Wnt signaling pathway in embryonic development and in regulation of tissue homeostasis, SFRP1 dysregulation is largely associated with cancer development, including breast cancer." (PMID 32967276, 2020). "Loss of SFRP1 has been detected in hepatocellular carcinoma, colon cancer, breast cancer, and many other cancers associated with poor prognosis." (PMID 32076068, 2020). "The majority of studies have reported that SFRP1 loss is correlated with poor prognosis in breast cancer, lung cancer, cholangiocarcinoma, and hepatocellular carcinoma." (PMID 32764696, 2020). "The overexpression of SFRP1 has been described in basal-like breast cancer and associated with the presence of lymph node metastases and decreased overall survival in gastric cancer." (PMID 31195594, 2019). "This is line with earlier reports on sFRP1, downregulation of which is associated with poor prognosis and therapeutic response in breast cancers." (PMID 28373842, 2017). "We revealed that loss of Sfrp1 alters the growth and behavior of mammary epithelial in such a manner that they exhibit characteristics of breast cancer cells." (PMID 24885183, 2014). "Secreted frizzled-related proteins (SFRPs) are a family of proteins that block the Wnt signaling pathway and loss of Sfrp1 expression is observed in breast cancer." (PMID 24885183, 2014). "We also explored the Kaplan Meier Plot resource and noted that MDM2 and SFRP1 are positively associated with relapse free survival in all breast cancer subtypes, while TTK is negatively correlated with overall survival of Luminal A patients." (PMID 25278993, 2014). "There is a plethora of evidence of loss of SFRP1 expression in many cancers including breast cancer, suggesting that this gene acts as a mammary tumor suppressor." (PMID 25278993, 2014). "As published so far, reduced SFRP1 expression was significantly associated with unfavorable clinical outcome for breast cancer patients as well." (PMID 25036590, 2014). "SFRP1 has been linked to a number of solid tumors, e.g. colon cancer, ovarian cancer, prostate cancer or breast cancer." (PMID 25033833, 2014). "To identify genes affected by SFRP1 re-expression either in association with a distinct breast cancer subtype, or independently of those, we performed a comprehensive whole human genome expression and compared identified pattern." (PMID 25036590, 2014). "It has previously been shown that loss of SFRP1 alters the growth and behavior of mammary epithelial cells, in vitro and in vivo, in such a manner that they exhibit characteristics of breast cancer cells." (PMID 24339864, 2013).
breast carcinoma (continued). "Secreted frizzled-related proteins (SFRPs) are a family of proteins that block the Wnt signaling pathway and loss of SFRP1 expression is found in breast cancer along with a multitude of other human cancers." (PMID 22928951, 2012). "Secreted frizzled-related protein 1 (SFRP1) antagonizes this pathway and loss of SFRP1 expression is frequently observed in breast tumors and breast cancer cell lines." (PMID 21303533, 2011). "For example, methylation of the Wnt antagonists SFRP5 and SFRP1 in breast cancer is an independent risk factor for adverse patients survival." (PMID 20830311, 2010). "Loss of SFRP1 expression is observed in breast cancer, along with several other cancers, and is associated with poor patient prognosis." (PMID 19422694, 2009). "Compelling evidence suggests that activation of Wnt signaling plays an important role in breast cancer, and that loss of SFRP1 function is a key mechanism by which Wnt signaling is activated under such circumstances." (PMID 19995452, 2009). "The WNT signaling pathway plays an important role in development and tissue homeostasis, and its aberrant activation by loss of expression WIF1 or SFRP1 has been shown to be an important early event in breast cancer progression." (PMID 19187537, 2009). "In previous studies, loss of SFRP1 was found to be associated with cancer progression and poor prognosis in breast cancer." (PMID 19116033, 2008). "Taken together, these results suggest that loss of SFRP1 function is a key mechanism by which Wnt signalling is activated in breast cancer." (PMID 18283316, 2008). "In breast cancer, several genes encoding inhibitors of canonical Wnt/β-catenin signalling have been reported to be frequently hypermethylated, for example, SFRP1, SFRP2, SFRP5, WIF1 and DKK1." (PMID 18826564, 2008). "The loss of SFRP1 is known to be associated with breast cancer progression and poor prognosis in early stages, and a similar expression profile is seen in our study." (PMID 17389037, 2007). "Moreover, loss of SFRP1 expression is associated with poor overall survival in patients with breast cancer." (PMID 38554160, 2024). "Methylation of SFRP1 is associated with poor prognosis in ER+/HER2+ breast cancers." (PMID 37091166, 2023). "However SFRP1 expression was associated with luminal breast cancer outcomes specifically, expressing ERα and/or PR, corroborating the existence of a crosstalk between the Wnt signaling pathway and the ERα signaling pathway during breast carcinogenesis." (PMID 37190179, 2023). "Finally, we examined the association between SFRP1 expression in tumoral tissue and patients’ outcomes after stratification for ERα status or breast cancer molecular subtypes." (PMID 37190179, 2023). "In addition, we analyzed the causal role of SFRP1 modulations of expression by lentiviral transduction on early breast carcinogenesis and breast cancer aggressiveness in vitro." (PMID 37190179, 2023). "In this condition, it is possible that SFRP1 function switches to engage in microcalcifications’ destruction, resulting in a pathological chronic inflammation responsible for the increased risk of breast cancer development." (PMID 32967276, 2020). "Regarding a potential role of SFRP1 in breast involution and considering the protective role of mammary involution against breast tumorigenesis, SFRP1 could be a crucial player, to optimize lobular involution and decrease breast cancer risk." (PMID 31947616, 2020). "However, a high expression level of SFRP1 was associated with better prognosis in patients with breast carcinoma, esophageal adenocarcinoma, head and neck squamous cell carcinoma, kidney renal clear cell carcinoma, and pancreatic ductal adenocarcinoma." (PMID 32764696, 2020). "Here, we investigated whether exercise training causes changes in the serum levels of DKK1 and SFRP1 in patients with breast cancer." (PMID 28178355, 2017).
breast carcinoma (continued). "However, in line with our findings, studies on tumor tissue regarding breast cancer and renal cancer have suggested SFRP1 hypermethylation to be an independent risk factor for low overall survival." (PMID 29212200, 2017). "In addition, we confirmed that in breast cancer the downregulation of SFRP1 associated with promoter methylation." (PMID 28218291, 2017). "SFRP1 encodes the secreted frizzled-related protein 1 which is a soluble Wnt antagonist, and its inactivation is known to be associated with unfavorable prognosis among breast cancer patients." (PMID 27786176, 2016). "For instance, downregulation of SFRP1 has been associated with tumor progression in breast cancer." (PMID 26337084, 2015). "We could demonstrate that breast cancer cell lines showing increased SFRP1 expression are associated with the triple negative phenotype, similar to published results showing higher expression in basal like cancer cell lines compared to luminal cell lines." (PMID 25033833, 2014). "In conclusion, SFRP1 re-expression caused distinct gene signature pattern in dependency of a given breast cancer subtype, potentially by affecting either the canonical Wnt pathway in basal-like breast cancer cells or the non-canonical Wnt pathway in luminal-like breast cancer cells." (PMID 25036590, 2014). "Collectively, these data indicate that loss of Sfrp1 may be a critical early event in obesity associated breast cancer initiation." (PMID 24339864, 2013). "Loss of SFRP1 expression is found in a multitude of cancers including breast cancer." (PMID 21303533, 2011). "Moreover, loss of SFRP1 expression is associated with poor overall survival in patients with early breast cancer." (PMID 19422694, 2009). "Currently, it is unknown whether SFRP1 loss causes the mammary gland to be predisposed to breast cancer development." (PMID 19422694, 2009). "We therefore next used siRNA (siSFRP1) to disrupt SFRP1 expression in a breast cancer cell line (MDA-MB-436) and tested whether loss of SFRP function leads to upregulated Wnt signalling." (PMID 18283316, 2008). "SFRP1 inactivation in breast cancer is associated with poor prognosis." (PMID 16933995, 2006). "The high expression of mRNA SFRP1 has been associated with poor prognosis in lung squamous cell carcinoma and correlated with a better prognosis for patients with other types of cancer, including breast carcinoma, oesophageal adenocarcinoma, or head and neck squamous cell carcinoma." (PMID 37999144, 2023). "Indeed, loss of SFRP1 increases Wnt signaling in mammary epithelial cells, a deleterious effect considering that inappropriate activation of the Wnt/β-catenin pathway contributes to the development of breast cancer." (PMID 24885183, 2014). "Interestingly, SFRP1 encodes a soluble Wnt antagonist and is located on chromosome 8p12-p11.1, which is a frequently affected region involving genetic alterations in some tumors, including breast cancer, colorectal carcinomas, and HCC." (PMID 17626620, 2007). "A previous study explained the involvement of miR-27 in the migration and invasion of breast cancer by targeting the SFRP1 gene via the Wnt/β-catenin signaling pathway." (PMID 38999923, 2024). "The promoter hypermethylation is the predominant mechanism of SFRP1 gene silencing in breast cancer, importantly, our findings demonstrate this epigenetic mechanism again." (PMID 37963835, 2023). "Here, the reduction in SFRP1 correlates with activated Wnt-signalling while ectopic overexpression of SFRP1 in breast cancer cells blocks Wnt-signalling, decreasing the migratory potential and inhibiting anchorage-independent growth." (PMID 37402051, 2023). "SFRP1 is an antagonist of the oncogenic WNT signaling pathway, and miR-93-3p and miR-105 were reported to suppress SFRP1 expression to promote breast cancer cell stemness, chemoresistance, and metastases." (PMID 36674525, 2023).